FGFR4 (fibroblast growth factor receptor 4)
Diseases named in the same sentence as FGFR4 in open-access papers (continued):
Sharing a sentence is not in itself a finding about the gene and the disease.
tumor (continued). "Overexpression of FGFR-4 in vitro leads to increased invasion, while its downregulation results in decreased viability, invasion, and tumor formation." (PMID 33235319, 2020). "FGFR4 in the tumor tissues is significantly higher than that in normal liver tissues, and it is strongly associated with a higher TNM stage (T: tumor, N: lymph nodes, M: metastasis)." (PMID 32555680, 2020). "FGFR4 mRNA levels were higher when compared with the matched non-tumor tissues and western blot analysis showed increased FGFR4 expression in LSQ samples." (PMID 32111983, 2020). "In mediating tumor growth and development, overexpression of FGFR4 and amplification of its target receptor FGF19 play a significant role." (PMID 33456465, 2020). "In pancreatic neuroendocrine tumors (PNETs), transfection of FGFR4-G388R vector promoted tumor progression by increasing intraperitoneal spread and liver metastasis in immunodeficient mice." (PMID 33066597, 2020). "It is important to consider that FGF19/FGFR-4 signaling can alter the tumor microenvironment by modulating circulating endothelial cells via FGF19-dependent paracrine mechanisms and possibly soluble factors." (PMID 33235319, 2020). "LCM from SUM159 tumor-bearing mice contained 16 unique proteins relative to other LCM conditions, including the metastasis-associated proteins CCL7, FGFR4, GM-CSF, MMP3, thrombospondin-1 and VEGF." (PMID 31936750, 2020). "Two known pathogenic mutations associated also with urachal cancers; FGFR4 and KRAS and seven known mutations associated with a drug response were identified in the patient’s tumor cells." (PMID 32576176, 2020). "In the context of FGF19-dependent tumors, FGF19/FGFR-4 blockade with FGF401 resulted in tumor growth inhibition, reduction of cell proliferation, induction of apoptosis, and improved OS in both orthotopic and ectopic models." (PMID 33235319, 2020). "FGFR4 immunohistochemistry in pretreatment tumor has a possibility to predict the response to lenvatinib therapy." (PMID 33301055, 2020). "Overall, 26/29 (90%) metastases have an increase in FGFR4 RNA relative to their matched primary tumor (p = 4.7e−6), including 19/29 (66%) with a fold change >2." (PMID 31263748, 2019). "Due to broad ligand binding spectrum of FGFR4, it is reportedly involved in multiple tumor types including HCC, breast cancer, colorectal cancer, rhabdomyosarcoma, and lung cancer." (PMID 31167419, 2019). "Mechanistically, FGFR4‐triggered activation of the PI3K/AKT pathway played a key role in the PM‐accelerated progression of colonrectal tumor formation." (PMID 31179224, 2019). "The upregulation of FGFR4 in our tumor samples compared to normal tissues in Western blot supports previous results of the other study." (PMID 31408968, 2019). "High FGFR4 expression correlates with tumour progression and survival in patients with gastric cancer." (PMID 31601997, 2019). "In conclusion, the presence of both FGFR4 SNP rs2011077 and rs1966265 contributed to a higher probability of tumor progression in UCC." (PMID 31878098, 2019). "Collectively, these results suggest that FGFR4 is an upstream driver in triggering the PM‐induced neoplasia, both in vivo and in vitro." (PMID 31179224, 2019). "Correlation of clinicopathological parameters and expression of FGF8, FGF18, and FGFR4 in the tumor tissue revealed significant correlations of the FGF8 protein level with tumor size ((y)pT), UICC stage, and Mandard regression grade." (PMID 31527546, 2019). "Tumor cell expression of FGFR4 is confirmed in our preliminary IHC analysis, but more samples are needed to fully assess the correlation between RNA and protein levels in metastatic tissue and the contribution of FGFR4 RNA from stromal cells." (PMID 31263748, 2019). "IHC staining demonstrated depletion of FGFR4 expression in colonic tissues of Fgfr4−/− mice and significantly increased FGFR4 expression in tumor tissue of AOM/PM‐treated WT mice, compared with normal colon of FRA treated WT mice." (PMID 31179224, 2019).
tumor (continued). "It has been reported in other tumor models that silencing FGFR4-388Arg induces a mesenchymal-to-epithelial transition, suggesting a role for FGFR4-388Arg in EMT22,24." (PMID 29402970, 2018). "According to Fisher’s exact test results, overexpression of FGFR4 (P < 0.001) and KLB (P = 0.005) were significantly associated with a low tumor grade." (PMID 30593273, 2018). "In future work, we will collect the tumor samples from patients with sorafenib-sensitive or resistant HCC to explore clinical importance of the FGF19/FGFR4 axis." (PMID 28069043, 2017). "High FGFR4 expression correlated with tumor progression and survival in both types of GC, although FGFR1 and 2 correlated with these variables in only DGC." (PMID 28056982, 2017). "We found that FGFR4 mRNA expression was higher in tumor tissues than in normal tissues in various cancers." (PMID 29221201, 2017). "The expression level of CTLA4 only correlated with central tendency parameters, while expression of GLUL, FGFR4, tumour stemness markers KRT19 and EPCAM and immune checkpoint PDCD1 showed significant correlations with MRI heterogeneity parameters only." (PMID 28550313, 2017). "In our previous work, we have provided evidence that FGF19 secreted from either HCC cells or tumor microenvironment can activate its specific receptor FGFR4 on the surface of HCC cells." (PMID 28069043, 2017). "Inhibition of the FGFR4/FGF19 signaling induces tumor-specific cell death in cancer cells that express them." (PMID 27192118, 2016). "CD15/FUT4 overexpression is driven by constitutive oncogenic signalling pathways in the tumor cells (innate immune resistance) acting as a novel RAF-MEK-ERK kinase downstream regulator through ERBB3 or FGFR4 activation, respectively." (PMID 26427914, 2015). "Thus, the finding that PTEN methylation/mutation is highly specific to and frequent in the E1/E2 tumours indicates that PTEN may serve as a diagnostic marker to identify those patients for which inhibition of the FGFR4/PI3K/AKT axis could have a key therapeutic role." (PMID 26138366, 2015). "Genome wide, this tumor had 3,889 somatic mutations including oncogenic mutation KRAS G13D and FGFR4 V550L." (PMID 25768946, 2015). "Amplification and mutational activation of Fibroblast Growth Factor Receptor 4 (FGFR4) in RMS cells promote tumor progression." (PMID 26420980, 2015). "These mutations occur at amino acid 535 and 550 of the kinase domain and promote tumor growth and metastasis in vivo by constitutively activating FGFR4." (PMID 24124571, 2013). "Then, we used FGFR4-silenced cells to study the dependence on FGFR4 for tumor growth in mouse xenografts." (PMID 23696849, 2013). "After 10 days of treatment, the tumor sizes of mice bearing the two mutant FGFR4 RMS772 cell lines were significantly smaller compared to their untreated counterpart." (PMID 24124571, 2013). "Amplification and mutational activation of FGFR4 has been reported in RMS and promotes tumor progression." (PMID 24124571, 2013). "Some studies of FGFR4 in mitogenicity and tumor development suggest that the role of FGFR4 is insignificant or even suppressive in tumorigenesis." (PMID 24279986, 2013). "Even in tumor foci where ADIPOQ was drastically depressed more than 100-fold, ADIPOQ was increased 11-fold by FGFR4 deficiency." (PMID 24279986, 2013). "To test the role of the FGF19/FGFR4 system in tumor progression, we used recombinant FGF19 protein and small interfering RNA (siRNA) of FGF19 and FGFR4 to regulate their concentrations." (PMID 22309595, 2012). "In this study, we built upon our previous work by focusing on FGFR4 signaling and have uncovered a novel molecular mechanism amplifying FGFR4 activity, further corroborating a tumor-progressive role of dysregulated FGFR4 activity in HCC." (PMID 22439738, 2012). "Blocking FGFR4 expression decreased RMS tumor size, cell migration, and metastasis, therefore characterizing FGFR4 as a possible molecular target for RMS." (PMID 21253475, 2011).
tumor (continued). "A similar configuration has been observed between FGFR4, N-CAM and N-cadherin in tumour cell migration, providing a mechanistic explanation of the impact FGFR4 has on several tumour types." (PMID 20234367, 2010). "A similar observation was made when tumours with strong FGFR4 expression was stratified by differences in Sef expression level." (PMID 19888221, 2009). "Studies that have examined the role of FGFR4 in the carcinogenesis provide evidence for the complexity of the FGF/FGFR signalling pathway in different tumour types." (PMID 17519899, 2007). "Strong reactivity for FGFR4 was found in 4 cases (7%), while 51 tumours (83%) displayed intermediate and 6 (10%) only minimal staining intensities." (PMID 16721364, 2006). "Both low to moderate-grade and high-grade tumours had significantly higher expression of FGFR4 than BPH (P<0.0004 and <0.0000l, respectively)." (PMID 15655558, 2005). "Resistance may be developed by tumor cells through the induction of structural changes in the FGFR4 protein, especially within the ATP-binding pocket, which prevents accurate inhibitor binding." (PMID 41328353, 2026). "However, hLD1.vB, a humanized antibody, exhibited inferior antitumor efficacy, with only a 14% reduction in tumor volume, despite having similar binding affinity to FGFR4 as chLD1." (PMID 41328353, 2026). "These ADCs may provide a selective approach to delivering cytotoxic agents specifically to FGFR4-positive tumor cells, thereby reducing off-target toxicity and offering a promising immunotherapeutic strategy for the treatment of RMS, HCC, and BC." (PMID 41328353, 2026). "High expression of FGF19 is not only associated with increased clonogenicity and stem cell-like properties of GBM cells, but also with enhanced tumor invasiveness, mediated by alterations in cell adhesion and activation of the integrin signaling pathway via FGFR4." (PMID 41328353, 2026). "Targeting FGF19 holds therapeutic potential for modulating tumor metabolism by inhibiting the FGFR4-ERK pathway, thereby reducing the expression of key fatty acid synthesis enzymes, such as FASN and ACC, and ultimately disrupting the metabolic support for tumor proliferation." (PMID 41328353, 2026). "However, when combined with pharmacological inhibition of myeloid components in the tumor stroma, FGFR4 CAR-T cells can eliminate orthotopic RMS tumors in mouse models." (PMID 41328353, 2026). "FGF19, FGF19-reaction (increase), Ang-2-Reaction (decrease), ST6GAL1, Tumor-FGFR4." (PMID 40164125, 2025). "The xenografted mice with CT-26/FGFR4 showed a marked increase in tumor growth and weight." (PMID 40447617, 2025). "Moreover, targeted therapies that inhibit FGF receptor 4 (FGFR4) can enhance the effectiveness of anti-PD-1 therapy by reducing PD-L1 expression and impeding Treg differentiation, further augmenting the anti-tumor immune response." (PMID 40432892, 2025). "FGFR4 is widely overexpressed in human epithelial carcinomas, where it may contribute to tumor progression by various mechanisms." (PMID 40806692, 2025). "FGFR4 promotes tumor progression by binding to its ligands, including FGF19, and upregulates downstream signaling cascades such as Ras-Raf-MAPK and PI3K-AKT to regulate cell growth, differentiation, and survival, together with cell migration by inducing epithelial–mesenchymal transition (EMT)." (PMID 40447617, 2025). "There was a weak positive correlation between the H-score and Ki-67 (p = 0.011; r = 0.201), and the authors concluded that higher levels of FGFR4 in PA could be used as a marker for more aggressive tumor behavior." (PMID 40806692, 2025). "We then tested the therapeutic effect of FGFR4 after tumor formation in vivo." (PMID 41213916, 2025). "Importantly, ADAMTSL5 confers tumorigenicity by upregulating oncogenic inputs (i.e., MET, EGFR, PDGFRβ, IGF1Rβ, FGFR4), and its abrogation increases sensitivity of tumor cells to clinically relevant drugs." (PMID 38495872, 2024).
tumor (continued). "Moreover, the high expression of FGFR4 was correlated with bigger tumor size, more lymph node metastasis, and advanced tumor stage, which were clinical parameters related to worse prognosis." (PMID 39658878, 2024). "Furthermore, the Nb-derived CAR-T cells, targeting FGFR4, exhibited significantly enhanced anti-tumor efficacy in both experiments when in vitro and in vivo." (PMID 38610029, 2024). "Knockdown of FGFR4 could greatly inhibit tumor growth and metastasis via suppressing the PI3K/AKT signaling." (PMID 39658878, 2024). "Elevated expression of FGFR4 in cancers could result in enhanced cell proliferation and tumor growth." (PMID 39658878, 2024). "Furthermore, to identify genes that were preferentially expressed in tumor-infiltrating T-cells expressing FGFR4.28HTM.28z-CD276.8HTM.BBz BiCisCAR, we performed a differential expression analysis." (PMID 39043633, 2024). "Finally, we explored the FGFR4 expression differences between tumor and normal tissues in pan‐cancer cohorts (TCGA + GTEx) and found that FGFR4 was widely upregulated in multiple malignancies." (PMID 39658878, 2024). "Thus demonstrating the importance of FGFR4 as a pharmacological treatment for the inhibition of cancer in both in vitro and in vivo studies and as an inhibitor of tumor proliferation and invasion." (PMID 38540215, 2024). "Furthermore, the proportion of T-cells transduced with FGFR4.28HTM.28z-CD276.8HTM.BBz BiCisCAR that expressed exhaustion markers was significantly lower within tumor (CD39 and Tim-3) and in the blood (CD39 and LAG-3) compared to those observed with other CARs." (PMID 39043633, 2024). "Bicistronic CARs (BiCisCAR) targeting both FGFR4 and CD276, containing two distinct co-stimulatory domains, have superior prolonged persistent and invigorated anti-tumor activities compared to the optimized FGFR4-specific CAR and the other BiCisCAR with the same 4-1BB co-stimulatory domain." (PMID 39043633, 2024). "PI3K/AKT was reported to be activated by FGF19/FGFR4 and involved in tumour progression." (PMID 37782406, 2024). "In 5 of 68 (7%) of tumor samples, novel whole-exome sequencing data identified alterations in the fibroblast growth factor receptor 4 (FGFR4) as a potential therapeutic target based on high expression, recurrent amplification, and recurrent activating mutations." (PMID 39411551, 2024). "The limited efficacy of improved FGFR4 CAR against RMS559 tumor may be due to the heterogeneous expression of FGFR4 expression on RMS." (PMID 39043633, 2024). "In addition, from the TCGA database, we found that FGFR4 expression was higher in LIHC tumor tissues than in para-cancer liver tissues, and higher FGFR4 expression was closely associated with poorer prognosis in HCC patients." (PMID 37085881, 2023). "This discrepancy between in vitro and in vivo experiments indicated that FGF19 could promote CRLM through mechanisms other than tumor cell regulation via FGFR4." (PMID 37345586, 2023). "Also, HER2 protein overexpressing tumours showed significantly higher expression of several receptor tyrosine kinases (RTKs) including FGFR4, EGFR, HER2 itself, as well as genes within the HER2 amplified region on Chr17q12-q21 (including GRB7)." (PMID 37740038, 2023). "Interestingly, a much lower expression of FGFR4 was observed in tumor xenografts-derived Rh4 cells (twofold over isotype control) compared to cultured wild-type Rh4 cells (97-fold over control)." (PMID 37924157, 2023). "This includes FGFR4 (fibroblast growth factor receptor 4), whose activating mutations are present in 7% of FP RMS patients, triggering RAS and STAT signaling pathways that induce tumor growth." (PMID 37958442, 2023). "Hence, we sought to evaluate the function of FGFR4 in ccRCC, with a focus on its direct effects on tumour cell proliferation and the potential of selective pharmacological FGFR4 inhibition as a therapeutic strategy." (PMID 36803783, 2023).
tumor (continued). "So far, most studies have mainly focused on the aberrant activation of FGF19–FGFR4 signalling in HCC,8, 9 but the regulation mechanism of FGFR4 expression in tumour progression is still largely unknown." (PMID 37846441, 2023). "In addition, we found that FGFR2, FGFR3 and FGFR4 expression was increased in the tumour tissues compared to that in normal tissues in the TCGA_LIHC datasets." (PMID 37846441, 2023). "Moreover, patients showing modifications of CEBPA, FGFR4, MET or KMT2B genes detected in circulating tumor DNA before ICI initiation are at higher risk of experiencing irAEs." (PMID 36900420, 2023). "Additionally, in a xenograft model of HCC, the coadministration of the cyclin-dependent kinase 4/6 inhibitor palbociclib in combination with FGFR4-selective inhibitors facilitated tumor regression, which indicates a potential new strategy for HCC treatment." (PMID 36980566, 2023). "In summary, our study revealed that the co-administration of FGFR4 inhibitor with EZH2 inhibitor could significantly inhibit tumor growth, which may be a potential option for the future clinical treatment of HCC." (PMID 37085881, 2023). "In CRC, CAF-derived CCL2 upregulates FGFR4, which plays a role in tumor-matrix interactions and promotes EMT, which may constitute an essential factor in CRC resistance to 5-FU and oxaliplatin." (PMID 35740594, 2022). "Taken together, these results propose that MAEL may promote EOC cell invasion and tumor metastasis via regulation of FGFR4." (PMID 35513870, 2022). "Furthermore, the analysis of paired samples from the TCGA database suggested that only FGFR4 expression was significantly elevated in tumor samples." (PMID 36147913, 2022). "FGFR4 blockade significantly reduced tumor growth and progression in subcutaneous murine and in zebrafish xenografts, respectively, and completely diminished tumor formation in mouse brains." (PMID 35484633, 2022). "While repression of “basalness/squamousness” seems an intrinsic feature of FGFR4, we also showed that its silencing in FGFR4low basal-like models increases malignant behaviour suggesting a bona fide tumour suppressive role for endogenous levels of FGFR4 in PDAC." (PMID 35963908, 2022). "Moreover, we present evidence that MAEL promotes tumor invasion and metastasis through upregulation of FGFR4." (PMID 35513870, 2022). "Consistent with the FGF19/FGFR4 downstream pathway, tumor PD assessed by RNAseq revealed an upregulation of CYP7A1 transcript concomitant with downregulation of the MAPK target gene DUSP6, in most on-treatment biopsies obtained at C1D8 with respect to the matched pretreatment sample." (PMID 35655320, 2022). "Finally, we downregulated FGFR4 in the organoid model of FGFR4low basal-like tumours (PDA9-O) prior to in vivo transplantation in immunocompromised hosts." (PMID 35963908, 2022). "Moreover, the nude mice bearing FGFR4 overexpression tumors (N87-FGFR4) showed better tumor-growth promotion than those with the control plasmid." (PMID 36147913, 2022). "In contrast, FGFR4 expression was negatively correlated with tumor-infiltrating lymphocytes." (PMID 36147913, 2022). "As EMT has been widely accepted as a cellular event to be associated with tumor initiation, we further used BLU9931 to study whether blocking FGFR4 could inhibit EMT event in FGF21KD FL83B cells either with PA challenging or without." (PMID 34326695, 2021). "Lenvatinib can also reduce tumor PD-L1 level to improve anti-PD-1 efficacy by blocking FGFR4." (PMID 34568339, 2021). "Moreover, the simultaneous targeting of FGFR4 and other receptor tyrosine kinases (RTKs) has been shown to indirectly enhance anti-tumor activity through normalization of the tumor microenvironment." (PMID 34576070, 2021).